SUN1 (Sad1 and UNC84 domain containing 1)
Diseases named in the same sentence as SUN1 in open-access papers (continued):
Sharing a sentence is not in itself a finding about the gene and the disease.
HIV-1 infection (2 papers, 2017 to 2021). The type species of lentivirus and the etiologic agent of acquired immunodeficiency syndrome (AIDS). "Previous observations have shown that overexpression of SUN1/2 proteins blocks HIV-1 infection after reverse transcription but before integration." (PMID 34580332, 2021). "In agreement, we showed that overexpression of SUN1 (Sad1 and UNC-84a) also blocks HIV-1 infection in a capsid-dependent manner." (PMID 34580332, 2021). "Overall these experiments suggested that SUN1 residues 20–100 are important for the ability of SUN1 to block HIV-1 infection." (PMID 34580332, 2021). "This work provides mechanistic understanding on how the overexpression of SUN1/2 proteins block HIV-1 infection in human cells." (PMID 34580332, 2021). "To test the ability of SUN1 to block HIV-1 infection, we challenged human HT1080 cells stably expressing SUN1 with increasing amounts of HIV-1-GFP." (PMID 34580332, 2021). "Overexpression of SUN1 in human cells potently inhibit HIV-1 infection after reverse transcription but prior to integration." (PMID 34580332, 2021). "Although overexpression of SUN2 blocks HIV-1 infection, we observed that this block is less potent when compared to SUN1." (PMID 34580332, 2021). "Our previous experiments suggested that the N-terminal domain of SUN1 is required for its ability to block HIV-1 infection, which is in agreement with the fact that HIV-1 can only interact with the N-terminus of SUN1 in the nucleoplasm." (PMID 34580332, 2021). "Mutational analysis demonstrated that the amino-terminal domain of SUN1 is important for the observed block of HIV-1 infection." (PMID 28747499, 2017). "In agreement with the hypothesis that the N-terminal domain of SUN1/2 are important for restriction, we found that deletion of N-terminal residues renders SUN1/2 inactive against HIV-1 infection." (PMID 34580332, 2021). "Interestingly, our experiments demonstrated that the SUN1 block to HIV-1 infection is after the viral core has been transported into the nuclear compartment, which is in agreement with the notion that SUN1 interacts with the HIV-1 core in the nucleus." (PMID 34580332, 2021). "Although several laboratories have attempted depletion of this protein further experiments will be necessary to establish whether endogenous expression of SUN1/2 contribute to HIV-1 infection." (PMID 34580332, 2021). "This is in agreement with our hypothesis that the N-terminal domain of SUN1 is important for its ability to bind capsid and restrict HIV-1 infection." (PMID 34580332, 2021). "One hypothesis is that the N-terminal domain of SUN1 is interacting with the HIV-1 replication complex in the nucleus consequentially affecting HIV-1 infection." (PMID 34580332, 2021). "We found that ectopic expression of UNC-84A/SUN1 or UNC-84B/SUN2 inhibits HIV-1 infection." (PMID 28747499, 2017). "We investigated whether the amino terminus of SUN1 is sufficient to inhibit HIV-1 infection by generating a fusion protein with the MLV restriction factor Friend virus susceptibility factor 1 (Fv1n)." (PMID 28747499, 2017). "We next sought to address the role of endogenous SUN1 or SUN2 proteins in HIV-1 infection." (PMID 28747499, 2017). "Taken together, these observations suggest that SUN1 and SUN2 may function redundantly to modulate postentry, nuclear-associated steps of HIV-1 infection." (PMID 28747499, 2017). "We speculate that SUN1/SUN2 may function redundantly in early HIV-1 infection steps and therefore influence HIV-1 replication and pathogenesis." (PMID 28747499, 2017). "To understand weather the subcellular localization of SUN1 and SUN2 are important for their ability to block HIV-1 infection, we analyzed subcellular localization of the different SUN1 and SUN2 variants." (PMID 34580332, 2021). "To explore the role of capsid in the ability of SUN1 and SUN2 (SUN1/2) to block HIV-1 infection, we measured the ability of SUN1/2 to bind to the HIV-1 core." (PMID 34580332, 2021).
HIV-1 infection (continued). "An overexpression screen identified the inner nuclear membrane proteins SUN1 and SUN2 as potential effectors of HIV-1 infection." (PMID 28747499, 2017). "We addressed the contributions of the endogenous SUN1 and SUN2 proteins to HIV-1 infection in the myeloid cell line THP-1 by generating single-cell clones in which SUN1 or SUN2 had been knocked out." (PMID 28747499, 2017). "We found that the integral transmembrane proteins SUN1/UNC84A and SUN2/UNC84B are potent or modest inhibitors of HIV-1 infection, respectively, and that suppression corresponds to defects in the accumulation of viral cDNA in the nucleus." (PMID 28747499, 2017). "Overexpression of SUN1 or SUN2 blocks HIV-1 infection; however, the role of endogenously expressed SUN1 and SUN2 in HIV-1 replication is not clear." (PMID 34580332, 2021). "We found that HAP1 SUN1, SUN2, or SUN1/SUN2 knockout cells were permissive to HIV-1 infection, suggesting that this system is not providing evidence for a functional contribution of SUN1 or SUN2 to HIV-1 infection." (PMID 34580332, 2021). "For this purpose, we generated knockouts for the expression of SUN1 and/or SUN2 in human haploid HAP-1 cells, and investigated whether HIV-1 infection is affected." (PMID 34580332, 2021). "In conclusion, we propose that the amino-terminal domains of SUN1 and SUN2 may interact with incoming HIV-1 subviral CA-containing replication complexes and facilitate steps during early HIV-1 infection, possibly in a redundant fashion." (PMID 28747499, 2017). "The depletion of SUN1 had no observable effect on infection by either virus, whereas the loss of SUN2 resulted in an ∼2- to 3-fold reduction in HIV-1 infection compared to a CRISPR/Cas9 control cell clone expressing an irrelevant control gRNA." (PMID 28747499, 2017). "It is possible that SUN1 and SUN2 provide redundant functions for HIV-1 infection; however, simultaneous depletion of both proteins can result in mitotic defects and delayed cell proliferation, thus confounding the interpretation of virus infection experiments." (PMID 28747499, 2017). "The results suggest that the CypA effects on HIV-1 infection are not changed by SUN1 or SUN2 gene knockout." (PMID 28747499, 2017). "We also tested untagged SUN1 and observed a similarly strong block to HIV-1 infection (data not shown)." (PMID 28747499, 2017). "In the same manner as SUN1, we tested the hypothesis that the N-terminal domain of SUN2 is interacting with the HIV-1 replication complex in the nucleus consequentially affecting HIV-1 infection." (PMID 34580332, 2021). "These experiments suggested that expression of SUN1 and/or SUN2 is not important for HIV-1 infection of HAP-1 cells." (PMID 34580332, 2021). "Our data suggested that the viral determinant for SUN1- as well as SUN2-mediated inhibition of HIV-1 infection is located in the HIV-1 CA protein; for example, HIV-1 harboring the CA from SIVmac was largely insensitive to SUN1 (data not shown)." (PMID 28747499, 2017). "While overexpression of SUN1 or SUN2 blocked HIV-1 infection, gene disruption in THP-1 cells had no (SUN1) or modest (SUN2) effects on HIV-1 infectivity, possibly indicating redundancy between the two proteins." (PMID 28747499, 2017). "Although our work shows that overexpression of SUN1 and SUN2 block HIV-1 infection, we did not yet address whether endogenous expression of these proteins are important for HIV-1 infection." (PMID 34580332, 2021). "Next, we tested whether cells that do not endogenously expressed SUN1 and SUN2 protein plays a role on HIV-1 infection." (PMID 34580332, 2021).
alopecia (1 paper, 2017). Hair loss usually from the scalp. "Deletion of Sun2, a functional homologue of Sun1, also showed aberrant nuclear position, altered desmosome distribution, and mechanically defective adhesions resulting in defective hair follicle structure and alopecia." (PMID 28595999, 2017).
angina (1 paper, 2025). "Similarly, the methylation levels at cg14480594 in the ACTL7A gene, cg17387122 in the MICAL3 gene, and cg02787562 in the SUN1 gene, which are associated with PM10, were significantly positively correlated with the risk of MI, angina, and HF, respectively (FDR < 0.05)." (PMID 41420191, 2025).
bipolar disorder (1 paper, 2015). A disorder of the brain that causes unusual shifts in mood, energy, activity levels and the ability to carry out day-to-day tasks. "Therefore, future research addressing whether mice that are deficient in Sun1 and/or Sun2, or Syne1 and/or Syne2 show cognition phenotypes such as schizophrenia or bipolar disorder could be beneficial in the field of psychiatric medicine." (PMID 26035387, 2015).
bladder cancer (1 paper, 2025). "Similarly, AFM measurements showed that human bladder cancer cells depleted of the chromatin-tethering proteins SUN1/2 had reduced viscoelastic response." (PMID 40823810, 2025).
breast tumor (1 paper, 2015). "The results showed that expression of SUN1, SUN2, nesprin-2, and lamin A/C mRNA in breast tumor was lower than mammary gland tissue." (PMID 26175118, 2015).
CREST syndrome (1 paper, 2024). "Centromeres were stained using autoantibodies specific to centromeres found in CREST syndrome (CREST), and the NE was visualized by co-staining of lamin A/C, a component of the nuclear lamina, and SUN1, a transmembrane protein localized at the INM." (PMID 38510147, 2024).
diabetes (1 paper, 2020). "To investigate the impacts of diabetes and exercise training on nuclear membrane proteins involved in nucleo-cytoskeleton, we next evaluate the levels of Nesprin-1 and SUN1." (PMID 32457392, 2020). "That is, neither diabetes nor endurance training caused a significant change in the levels of the SUN1 in the soleus and the EDL muscles (p > 0.05)." (PMID 32457392, 2020). "In this study, no changes in SUN1 protein were observed due to diabetes and endurance training." (PMID 32457392, 2020).
Dystonia (1 paper, 2011). An abnormally increased muscular tone that causes fixed abnormal postures. "We have demonstrated an association between the DYT1 dystonia protein, torA-ΔE, and the SUN1 component of the LINC complex." (PMID 21627841, 2011).
invasive breast carcinoma (1 paper, 2025). A carcinoma that infiltrates the breast parenchyma. "Lower lamin A/C and lamin B1 expression; decreased levels of emerin in invasive breast cancer; downregulation of SUN1, SUN2, and nesprin‐2; upregulation of LBR." (PMID 39866838, 2025).
leukemia (1 paper, 2021). A malignant (clonal) hematologic disorder, involving hematopoietic stem cells and characterized by the presence of primitive or atypical myeloid or lymphoid cells in the bone marrow and the blood. "SUN1 depletion stimulates the formation of alternative lengthening of telomeres-associated promyelocytic leukemia bodies in ALT cells." (PMID 33820871, 2021).
lung carcinoma (1 paper, 2015). "However, SUN1, another Sad1 and UNC84 domain protein in the LINC complex, is not significantly differently expressed between lung cancer tissues and normal lung tissues." (PMID 26658802, 2015).
myopia (1 paper, 2025). "In addition, actin, the molecular target of SUN1, is closely related to the induction of myopia through ocular AL elongation." (PMID 40149693, 2025).
Usher syndrome (1 paper, 2024). A syndromic diseae characterized by the association of sensorineural deafness (usually congenital) with retinitis pigmentosa and progressive vision loss. "Cad99C is homologous to the Usher syndrome gene PCDH15 while Msp300 and koi correspond to the nuclear membrane anchoring genes SYNE4 and SUN1, respectively." (PMID 38412189, 2024).
ZIKV infection (1 paper, 2024). "To explore whether SUNs participate in ZIKV infection, we generated two SUN1 and SUN2 knockout cell clones in Huh7 cells by CRISPR/Cas9 gene-editing technique." (PMID 38177122, 2024).
cancer (9 papers, 2015 to 2025). A tumor composed of atypical neoplastic, often pleomorphic cells that invade other tissues. "A notable example delved into the function of SUN1 in controlling cancer cells’ ability to remodel ECM barriers." (PMID 39866838, 2025). "Previous studies showed that SUN1, but not SUN2, is the main interactor of KASH-domain proteins in the LINC complex assembly and depleting SUN1 inhibits NE rupture in cancer cell lines." (PMID 39209536, 2024). "Several LINC-associated proteins such as SUN1, SUN2, Emerins and Nesprin-3 were seen to be differentially regulated in cancer cells exposed to simulated microgravity." (PMID 32942630, 2020). "By contrast, a recent study indicates that reduced levels of SUN1 and other LINC-associated components in cancer cells cause a decrease in cellular rigidity and, consequently, increase cell migration." (PMID 29690642, 2018). "This quantitation revealed that for all four proteins, most cancer tissues were in the low expression group: 85.1%, 88.4%, 74.4%, and 79.2% for lamin A/C, SUN1, SUN2, and nesprin-2, respectively." (PMID 26175118, 2015). "While Piezo1 facilitates the anti-cancer effects of ES, SUN1 acts as a negative regulator." (PMID 39940798, 2025). "Also, we further assessed the antitumor effect of SUN1/2 depletion in multiple mouse models of primary cancers induced by chemical compound or genetic manipulation." (PMID 37828059, 2023). "We therefore speculate that SUN1 + 2 knockdown leads to a softer nucleus in carcinoma cells, allowing them to squeeze through tight spaces encountered during invasion and metastasis." (PMID 34205257, 2021). "Changes in the levels of SUN proteins, particularly SUN1 and SUN2, also influence cancer cell migration, with tumor type‐dependent effects." (PMID 39866838, 2025). "To further investigate the link between SUN proteins, nuclear shape and motility in carcinoma cells, we disrupted LINC complex by knocking down SUN proteins (SUN1 and SUN2)." (PMID 34205257, 2021). "Anti-lamin A/C, anti-SUN1, anti-SUN2, and anti-nesprin-2 pAbs clearly stained noncancerous acini of terminal-duct lobular units adjacent to cancer cells at the nuclear membrane." (PMID 26175118, 2015). "In many cases, the staining intensities of SUN1, SUN2, and nesprin-2 were often weaker in cancer cells (middle column) than in noncancerous regions (left column); again, however, some cases exhibited normal expression (right column)." (PMID 26175118, 2015).
tumor (7 papers, 2015 to 2025). "SUN1 overexpression inhibited iTS cell generation, whereas its knockdown enhanced tumor-suppressive activity." (PMID 39940798, 2025). "In SUN1 + 2 knockdown tumor cells, we saw irregular shaped nuclei with nuclear envelope folds, invaginations, and blebs." (PMID 34205257, 2021). "Together, these results demonstrate that LINC complex disruption by SUN1 + 2 KD leads to 1D-specific increases in actin polymerization and tumor cell motility." (PMID 34205257, 2021). "Also, the lungs of Sun1/2DKO mice were substantially lighter than those of littermate controls, indicating that silencing of SUN1/2 expression markedly reduced tumor load." (PMID 37828059, 2023). "Interestingly, the same tumor cells showed 50% higher motility after SUN1 + 2 knockdown when moving in 1D environment." (PMID 34205257, 2021). "We treated tumor cell with either control siRNA or siRNAs for SUN1, SUN2 and MKL1." (PMID 34205257, 2021). "We treated tumor cells with control or SUN1 + 2 siRNA and plated them on 1D or 2D substrates." (PMID 34205257, 2021). "Next, we investigated the motility parameters of tumor cells in 1D after SUN1 + 2 KD." (PMID 34205257, 2021). "We investigated nuclear morphology in SUN1 + 2 KD tumor cells, and found that cells showed irregular nuclear morphology with multiple lobes, folds and membrane invaginations in both 1D and 2D, indicative of compromised nuclear mechanotransduction due to defects in nucleo-cytoskeleton integrity." (PMID 34205257, 2021). "In contrast, SUN1 knockdown enhanced CM’s tumor-suppressive effects, reducing viability and migration of MDA-MB-231 and MDA-MB-436 cells, suggesting that SUN1 acts as a negative regulator." (PMID 39940798, 2025). "Analysis using The Cancer Genome Atlas (TCGA) and the Genotype-Tissue Expression (GTEx) datasets showed downregulated expression of SUN1 and SUN2 across tumor types." (PMID 35663386, 2022). "In fact, using triple knockdowns (SUN1, SUN2, and MKL1) in tumor cells, we show that MKL1 is required for enhanced 1D motility of SUN1 + 2 KD cells." (PMID 34205257, 2021). "Analysis of The Cancer Genome Atlas dataset showed a dramatic decrease in the LINC complex proteins SUN1 and SUN2 in primary tumor compared to the normal tissue." (PMID 34205257, 2021). "Using smartpool siRNAs for SUN1 and SUN2, we efficiently knocked down SUN1 and SUN2 (referred to SUN1 + 2 KD hereafter) in tumor cells." (PMID 34205257, 2021). "SUN1 and SUN2 were recently identified as crucial mediators in remodeling the nucleus of macrophages during M1 polarization in response to inflammatory signals—a tightly regulated process whose imbalance often correlates with tumor progression." (PMID 39866838, 2025). "SUN1 and SUN2 are downregulated in tumors and exert tumor-suppressive effects." (PMID 36358787, 2022). "Since F-actin is the dominant cytoskeleton component regulating tumor cell migration, we investigated the changes in F-actin and G-actin (with specific antibody JLA20) levels in single tumor cells after SUN1 + 2 KD." (PMID 34205257, 2021). "Disruption of LINC complex by SUN1 + 2 KD led to multi-lobular elongated nuclei, increased tumor cell motility and concomitant increase in F-actin, without affecting Lamin proteins." (PMID 34205257, 2021). "The effects of MKL1 on tumor cell motility were specific to 1D, as we did not see any change in tumor cell 2D motility after SUN1 + 2 and MKL1 KDs." (PMID 34205257, 2021). "In cells moving on 2D substrates, no changes in tumor cell speed, persistence and actin polymerization were observed after SUN1 + 2 KD, indicating 1D-specific changes in cell motility and associated actin forces." (PMID 34205257, 2021). "Moreover, downregulation of SUN1 and SUN2 was observed across tumor types." (PMID 34205257, 2021). "However, in the tumor cells studied here, we did not see any changes in 2D cell motility after SUN1 + 2 knockdown." (PMID 34205257, 2021).